ILK (integrin linked kinase)
Diseases named in the same sentence as ILK in open-access papers (continued):
Sharing a sentence is not in itself a finding about the gene and the disease.
malignant glioma (1 paper, 2007). A grade III or grade IV glioma arising from the central nervous system. "Malignant gliomas often have high levels of Cyr61 associated enhanced tumorigenicity mediated through the integrin-linked kinase signaling pathway." (PMID 17579708, 2007).
memory impairment (1 paper, 2015). "The present study constitutes the first report highlighting the involvement of ILK in FASD-related memory impairments and synaptic plasticity." (PMID 26305322, 2015). "Furthermore, our study suggests that FASD-related memory impairments can be due to impaired ILK pathway." (PMID 26305322, 2015).
metastatic melanoma (1 paper, 2021). A melanoma that has spread from its primary site to another anatomic site. "A marked increase in both protein levels in metastatic melanoma cell 1205Lu is accompanied by lower autophagy induction after silencing of ILK, or by activation of pro-survival signals by an increase of Akt phosphorylation resulting from CQ treatment." (PMID 33916175, 2021).
myeloid leukemia (1 paper, 2012). A clonal proliferation of myeloid cells and their precursors in the bone marrow, peripheral blood, and spleen. "These intracellular signals are thought to require integrin-dependent activation of ILK (integrin-linked kinase), with subsequent recruitment of the MAPK and the phosphoinositide 3-kinase (PI3K)/Akt pathways, at least in myeloid leukemia." (PMID 22919401, 2012).
nonalcoholic steatohepatitis (1 paper, 2020). "Interestingly, TAZ has been shown to induce hepatocyte expression of Ihh in nonalcoholic steatohepatitis, and ILK has been shown to interact with Smo to mediate Hh signaling." (PMID 32910808, 2020).
occlusive vascular diseases (1 paper, 2010). "However, the regulatory role of ILK during vascular smooth muscle cell migration and the importance of integrin signaling in occlusive vascular diseases are not yet fully elucidated." (PMID 20178627, 2010).
osteopetrosis (1 paper, 2024). Osteopetrosis, also known as marble bone disease, is a descriptive term that refers to a group of rare, heritable disorders of the skeleton characterized by increased bone density on radiographs. "As both integrins support OC differentiation, dysfunction of either of the two integrins or of the signal transduction via integrin-linked kinase manifests in osteopetrosis." (PMID 39220682, 2024).
peripheral nerve injury (1 paper, 2021). Injury to a peripheral nerve. "Peripheral nerve injury activated a characteristic set of signaling pathways in both sexes, including HMGB1 Signaling, TREM1 signaling, IL-6 Signaling, IL-17 Signaling, Integrin signaling, HIF1α Signaling, Oxytocin Signaling, and ILK Signaling." (PMID 34966260, 2021).
pheochromocytoma (1 paper, 2015). "ILK activity is required to promote neurite growth factor (NGF) mediated neurite growth in rat pheochromocytoma cells; indeed, inhibition of ILK abolishes NGF-mediated neurite growth." (PMID 26305322, 2015).
polycystic kidney disease (1 paper, 2023). A usually autosomal dominant and less frequently autosomal recessive genetic disorder characterized by the presence of numerous cysts in the kidneys leading to end-stage renal failure. "We have shown that MMP9 protects from apoptosis, and it is known that both ILK and activation of FAK regulate cell proliferation in polycystic kidney disease." (PMID 38039285, 2023).
prostate tumours (1 paper, 2003). "Overexpression of ILK has been documented in a wide variety of human malignancies including Ewing's sarcoma (ES), primitive neural ectodermal tumours (PNETs) and prostate tumours (PT)." (PMID 12771992, 2003).
renal dysfunction (1 paper, 2024). "The good correlations between ILK content in circulating mononuclear cells and the renal function parameters tested in this study support the hypothesis that ILK can be considered a good biomarker of renal dysfunction." (PMID 38734696, 2024).
sarcoidosis (1 paper, 2020). Sarcoidosis is a multisystemic disorder of unknown cause characterized by the formation of immune granulomas in involved organs. "These proteins map to novel pathways such as integrin-linked kinase and IL-8 signaling and previously implicated pathways in sarcoidosis, including phagosome maturation, clathrin-mediated endocytic signaling and redox balance." (PMID 32764642, 2020). "We also identified novel pathways implicated in sarcoidosis such as signaling by integrin-linked kinase, IL-8, and caveolar-mediated endocytic signaling in our studies comparing BAL cells from controls and sarcoidosis cases." (PMID 32764642, 2020). "Thus, ILK-mediated mTOR activation could be a possible mechanism mediating inflammation in a subset of sarcoidosis cases." (PMID 32764642, 2020).
Sepsis (1 paper, 2025). Sepsis is defined as life-threatening organ dysfunction caused by a dysregulated host response to infection. "We hypothesize that this complex, through key elements KIND2 and ILK, plays a role in sepsis-induced-muscle-weakness." (PMID 41385533, 2025). "However, over the 5 days of sepsis, rAAV-shIlk1 treatment resulted only in the normalization of Ilk gene expression with no longer detectable changes in ILK protein levels." (PMID 41385533, 2025).
silicosis (1 paper, 2024). Silicosis is a respiratory disease caused by breathing in (inhaling) silica dust. "CRISPR/Cas9 technology to knockdown ITGB1 can inhibit the integrin/ILK signaling pathway and alleviate silicosis fibrosis, offering a fresh perspective on silicosis therapy." (PMID 39258668, 2024). "Through the integrin/ILK signaling pathway, silica can increase the expression of EMT-related proteins and promote the onset and progression of silicosis." (PMID 39258668, 2024).
Skeletal muscle hypertrophy (1 paper, 2017). Abnormal increase in muscle size and mass not due to training. "Integrin and ILK signaling pathways have been shown to play critical roles in both cardiac and skeletal muscle hypertrophy." (PMID 28845464, 2017).
small cell lung carcinoma (1 paper, 2023). Small cell lung cancer (SCLC) is a highly aggressive malignant neoplasm, accounting for 10-15% of lung cancer cases, characterized byrapid growth, and early metastasis. "Furthermore, the predictions of the small cell lung cancer pathway, neuroactive ligand–receptor interaction pathway, and integrin-linked kinase signaling pathway were consistent with several studies." (PMID 36980844, 2023).
Splenomegaly (1 paper, 2023). Abnormal increased size of the spleen. "Overall, these results demonstrate that myeloid-ILK pays critical roles in APCmin/+-driven physiological abnormalities including body weight loss, splenomegaly and poor survival." (PMID 38077324, 2023).
type 2 diabetes (1 paper, 2024). "In this study, the impacts of liraglutide on the integrin-linked kinase (ILK)-related PI3K/AKT axis in rats with type 2 diabetes induced via streptozotocin were examined." (PMID 38543160, 2024).
Ureteral obstruction (1 paper, 2023). Obstruction of the flow of urine through the ureter. "During the course of unilateral ureteral obstruction (UUO), tPA could trigger the clustering and interaction of Anxa2/CD11b, resulting in the subsequent activation of the integrin-linked kinase (ILK)-associated canonical nuclear factor-κB (NF-κB) pathway in macrophages." (PMID 37955107, 2023).
Ventricular arrhythmia (1 paper, 2021). "This indicated that ILK activation prevented I/R-induced-ventricular arrhythmia, an effect potentially related to inhibition of Cx43 remodeling via Akt activation." (PMID 32144627, 2021). "Our study showed that ILK activation prevented I/R-induced-ventricular arrhythmias, an effect potentially related to inhibition of Cx43 remodeling, through Akt activation." (PMID 32144627, 2021). "In our study, ILK prevented I/R-induced ventricular arrhythmias." (PMID 32144627, 2021). "We hypothesized that ILK, through Cx43 phosphorylation, would be protective against I/R-induced ventricular arrhythmias." (PMID 32144627, 2021). "In our study, ILK activation prevented I/R-induced ventricular arrhythmias." (PMID 32144627, 2021). "Thus, we hypothesized that ILK would inhibit I/R-induced ventricular arrhythmias." (PMID 32144627, 2021). "However, whether ILK can prevent I/R-induced ventricular arrhythmias is unknown." (PMID 32144627, 2021). "Our study showed that I/R-induced ventricular arrhythmias were attenuated by an ILK agonist LPTP and worsened by the ILK inhibitor Cpd22." (PMID 32144627, 2021). "While, in the presence of Akt inhibitor, MK2206, the protective effects of the ILK agonist, LPTP, on normalization of Cx43 distribution and ventricular arrhythmia were prevented." (PMID 32144627, 2021).
viral myocarditis (1 paper, 2020). Myocarditis that is caused by an infection with a viral agent. "It has been demonstrated for viral myocarditis, a disease that causes sudden cardiac death in children and young adults, ILK inhibition improves the viability of infected cells while blocking viral replication and virus release." (PMID 32268515, 2020).
cancer (202 papers, 2003 to 2026). A tumor composed of atypical neoplastic, often pleomorphic cells that invade other tissues. "Its homolog, LIMS1, forms a LIMS1-ILK-Parvin complex with integrin-linked kinase (ILK) and Parvin proteins and participates in the critical regulation of various cancers." (PMID 40755754, 2025). "TACC3 and ch-TOG have previously been shown to be involved in centrosome clustering in cancer cells, either via interaction with integrin-linked kinase or with KIFC1." (PMID 40105698, 2025). "ILK, a serine/threonine kinase, has been implicated in the oncogenesis and progression of human cancers by activating signaling pathways that promote cell proliferation, migration, and EMT." (PMID 38970088, 2024). "NETs interact with coiled-coil domain-containing protein 25 (CCDC25) on tumor cells and enhance cancer cell motility by activating the integrin-linked kinase (ILK)-β-parvin pathway." (PMID 39795864, 2024). "NET-DNA can bind to coiled-coil domain containing protein 25 (CCDC25) on cancer cells, activating the integrin-linked kinase (ILK)-β-parvin-ras-related C3 botulinum toxin substrate 1 (RAC1)-cell division control protein 42 (CDC42) cascade within cancer cells." (PMID 39143953, 2024). "In cancer cells, inhibition of integrin-linked kinase (ILK) increases centrosome declustering causing mitotic arrest and cell death." (PMID 37508338, 2023). "NETs‐DNA enhanced endogenous binding of ITGB4 to integrin‐linked kinase (ILK), a putative mediator of NETs‐driven cancer metastasis, leading to recruitment of β‐parvin, but not α‐parvin or PINCH, to mobilize the small GTPases RAC1 and CDC42." (PMID 37828611, 2023). "We observed that many adhesion associated genes, like LIMS1 (PINCH), ILK, or specific integrins, have only been marginally studied as cancer targets in radiation research." (PMID 37206618, 2023). "ILKAP is a protein serine/threonine phosphatase of the PP2C family linked to cancer through phosphorylation of integrin-linked kinase (ILK) thereby modulating downstream integrin signaling." (PMID 37732732, 2023). "Cancer-causing proteins such as integrin-linked kinase and Abelson kinase occur at abnormal centrosomes and these proteins are chemotherapeutic drug targets." (PMID 37508338, 2023). "Integrin-linked kinase (ILK) is overexpressed by many types of cancer cells and provides both structural and signaling functions that are important for successful metastasis." (PMID 35804980, 2022). "Many studies show that ILK overexpression is associated with the carcinogenesis and metastasis of diverse cancers, such as hepatocellular carcinoma, colorectal cancer and BC." (PMID 35029589, 2022). "Several ILK-mediated signaling pathways have been implicated in the regulation of EMT in cancer cells." (PMID 35804980, 2022). "It has been established that ILK overexpression and dysregulation are associated with the development and progression of different cancers including CRC." (PMID 35692780, 2022). "ILK has already been implicated in fibroblast and CAF regulation and in accord with this we found that ILK is significantly associated with CAF infiltration in different cancers with a notable correlation in COAD, STAD and LUSC." (PMID 35692780, 2022). "In our study, DC infiltration and their gene markers were associated with ILK expression in 28 cancer types and significantly with COAD, STAD and LUSC, but showed a weaker correlation in KIRC." (PMID 35692780, 2022). "Essentially, upregulation of ILK expression has been reported in human malignancies, being associated with poor prognosis of patients’ survival; thus, emphasizing its role in cancer diagnosis and prognosis." (PMID 35089438, 2022). "Stiff microenvironments can also stimulate signaling through integrin-linked kinase (ILK), leading to cancer stem cell (CSC) –like gene expression." (PMID 35631616, 2022).
cancer (continued). "Activation of intracellular kinases ILK/FAK has long been associated with the migration of cancer cells by promoting dynamic regulation of focal adhesions and peripheral actin structures." (PMID 35628269, 2022). "This cellular motility was mediated by the cancer cell-resident transmembrane NET-DNA receptor coiled-coil domain containing 25 (CCDC25) which activates the integrin-linked kinase (ILK)-β-parvin pathway and thus senses extracellular DNA release." (PMID 35574410, 2022). "The results showed that ILK expression is significantly associated with CAFs infiltration in most cancers." (PMID 35692780, 2022). "ILK expression was correlated with cancer-associated fibroblast (CAFs) and immunosuppressive cell infiltration including regulatory T cells (Treg) and M2 macrophages (M2) in addition to their gene markers." (PMID 35692780, 2022). "Accordingly, we investigated ILK association with CAFs in the TME across different cancers via the TIMER platform." (PMID 35692780, 2022). "In this review, we aim to focus on a possible association of ILK with cellular senescence regulation and cancer immunity in CRC." (PMID 34163519, 2021). "In this study, in metastatic breast (MDA-MB-231) and prostate (PC-3) cancer cells, we report that integrin-linked kinase (ILK) integrates β1-integrin with this signaling complex to regulate invadopodia activity and invasion." (PMID 33671549, 2021). "It has been established for about two decades that ILK overexpression and dysregulation are associated with development and progression of different cancers, including CRC." (PMID 34163519, 2021). "When integrin-linked kinase was neutralized in PMCs or PFBs, cancer cell adhesion to PMCs and PFBs decreased." (PMID 33921783, 2021). "Using IPA, many important cancer-related pathways were enriched in UC, including the tumor microenvironment pathway, Rho family GTPases, integrin-linked kinase signaling and activated protein kinase signaling." (PMID 34204134, 2021). "Catulin is also upregulated in highly invasive non-small cell lung cancer (NSCLC) cell lines, which promotes cancer cell migration, invasion, and metastasis through activating the integrin-linked kinase (ILK)-mediated Akt-NF-κB signaling." (PMID 35008571, 2021). "The EMT cellular process in cancer is regulated by diverse signaling pathways that have been implicated as being regulated either directly by ILK or indirectly via ILK downstream signaling pathways." (PMID 34163519, 2021). "Other enriched pathways include EMT itself, the IL-8 pathway, the integrin-linked kinase (ILK) pathway, and the actin cytoskeleton signaling,36,37which are all known to contribute to cancer-related EMT." (PMID 33792620, 2021). "Some other studies are showing that these molecules (β-catenin, GSK-3β, AKT, and ILK) are involved in normal biological events, and their overexpression is associated with cancer." (PMID 35317111, 2021). "Increased levels of ILK have been associated with cancer progression, epithelial to mesenchymal transition (EMT), angiogenesis, and metastasis." (PMID 32260415, 2020). "We report that targeting ILK with siRNA induces significant changes in the expression of several cancer-associated protein-coding genes and non-coding RNAs involved in cell growth, survival, and metastasis." (PMID 32260415, 2020). "Previous work has linked ILK to phosphorylation of PKB/AKT in cultured cancer cells and fibroblasts, which also reflects ILK-dependent cell–matrix interactions and integrin activation." (PMID 31748531, 2019). "Conversely, breast CSCs increase CSC marker expression on stiff matrix through integrin linked kinase (ILK) signaling, suggesting that the effect of matrix stiffness on stemness is cancer type specific." (PMID 31334229, 2019). "Among these, p56Lyn-, Akt-, and integrin-linked kinase (ILK)-mediated MCM7 phosphorylation primarily correlates with the development of human cancer." (PMID 30062004, 2018).